TACSTD2 (tumor associated calcium signal transducer 2)
Diseases named in the same sentence as TACSTD2 in open-access papers (continued):
Sharing a sentence is not in itself a finding about the gene and the disease.
hepatocellular carcinoma (7 papers, 2018 to 2024). A malignant tumor that arises from hepatocytes. "Strikingly, in hepatocellular cancer, TACSTD2-high tumors had a much lower prevalence of CTNNB1 mutations (25.0% vs 55.5%)." (PMID 38986529, 2024). "Finally, in hepatocellular cancer, TACSTD2 expression appeared to have the strongest association with the tumor immune microenvironment, but displayed few mutational associations and was not related to prognosis." (PMID 38986529, 2024). "The role of TACSTD2 in HCV infection was confirmed by immunofluorescence using a replication-competent variant of the HCV strain JFH1 (JFH1-AM2) selected in vitro for its efficiency of replication in hepatoma cells." (PMID 29538454, 2018). "TACSTD2-high hepatocellular cancer also displayed a greater fraction of M2 macrophages, dendritic cells, T regulatory (Tregs) cells, and B cells." (PMID 38986529, 2024). "Phosphorylated TACSTD2 bands were detected in both parental and TACSTD2-overexpressing Huh7.5 cells, indicating that in hepatoma cells the protein is functionally competent, as previously reported." (PMID 29538454, 2018). "In the present study, we documented that TACSTD2 is phosphorylated also in hepatoma cells and showed that the phosphorylated form of TACSTD2 interacts with CLDN1 and OCLN." (PMID 29538454, 2018). "Thus, we studied the phosphorylation status of TACSTD2 in hepatoma cells by immunoprecipitation with anti-TACSTD2 antibody followed by deglycosylation and Western blot analysis using a PKC substrate-specific antibody." (PMID 29538454, 2018). "To elucidate the spatial interactions between TACSTD2 and CLDN1, we examined their localization in hepatoma cells by confocal microscopy." (PMID 29538454, 2018). "To investigate the role of TACSTD2 in regulating CLDN1 and OCLN distribution in hepatoma cells, we performed TACSTD2 gene silencing using a pool of 4 siRNA (siTACSTD2) and examined the distribution of the two HCV-entry cofactors by confocal microscopy." (PMID 29538454, 2018). "TACSTD2 gene silencing disrupts the typical linear distribution of CLDN1 and OCLN along the cellular membrane in both hepatoma cells and primary human hepatocytes, recapitulating the pattern observed in vivo in primary HCC tissue." (PMID 29538454, 2018). "ICI in combination with TROP2-directed ADCs may be an attractive option for certain TACSTD2-high tumors, such as MSI-high CRC and hepatocellular cancer, where ICI has already seen success." (PMID 38986529, 2024). "The results of our gene silencing experiments demonstrated that TACSTD2 is involved in the maintenance of the proper cellular localization of two TJ proteins that are essential for HCV entry, CLDN1 and OCLN, both in hepatoma cells and in primary human hepatocytes." (PMID 29538454, 2018). "In both parental and TACSTD2-overexpressing Huh7.5 cells, CLDN1 was co-immunoprecipitated by an anti-TACSTD2 antibody, indicating that the two proteins interact, either directly or indirectly, in hepatoma cells." (PMID 29538454, 2018). "Since TACSTD2 was reported to interact with the HCV-entry cofactor CLDN1 in human corneal epithelial cells, we examined the interaction between TACSTD2 and CLDN1 in hepatoma cells by co-immunoprecipitation." (PMID 29538454, 2018).
liver cancer (6 papers, 2020 to 2024). An epithelial or non-epithelial malignant neoplasm that arises from the liver. "Conversely, TACSTD2 expression was higher in primary liver cancer compared to metastatic (P < .005)." (PMID 38986529, 2024). "In liver cancer PROM1 was more strongly co-expressed with a larger number of genes, including CFTR, KRT7, ANXA3, TACSTD2, and FZD1." (PMID 31164716, 2020).
gynecologic cancers (5 papers, 2021 to 2025). "In gastroenterological and gynecological cancers an increased TACSTD2 protein expression level was associated with adverse clinicopathology and poor outcome." (PMID 33882870, 2021).
endometrial endometrioid carcinoma (4 papers, 2012 to 2025). "Furthermore, hRS7, a human monoclonal anti-TACSTD2 antibody has been used in endometrial endometrioid carcinoma (EEC)." (PMID 25202389, 2014).
esophageal squamous cell carcinoma (4 papers, 2011 to 2024). Esophageal squamous cell carcinoma (ESCC) is a type of esophageal carcinoma (EC) that can affect any part of the esophagus, but is usually located in the upper or middle third. "Serological identification of TACSTD2 in patients with esophageal squamous cell carcinoma suggested that the TACSTD2 antigen may be a valuable serum tumor marker." (PMID 25202389, 2014). "CD44, TACSTD2, S100A14, and RHOD act as signatures to represent cancer‐spreading‐initiating cells in esophageal squamous cell carcinoma." (PMID 38864342, 2024).
macular corneal dystrophies (4 papers, 2019 to 2023). "For example, direct correlations have been established between mutations in CHST6, UBIAD1, SLC4A11, PIKFYVE, TACSTD2, and DCN with macular corneal dystrophies (MCD), Schnyder CD, congenital hereditary endothelial dystrophy, fleck CD, gelatinous drop-like CD, and congenital stromal CD, respectively." (PMID 31555324, 2019).
small cell lung carcinoma (4 papers, 2015 to 2025). Small cell lung cancer (SCLC) is a highly aggressive malignant neoplasm, accounting for 10-15% of lung cancer cases, characterized byrapid growth, and early metastasis. "Recent advances in the molecular characterization of small-cell lung cancer (SCLC) have led to the identification of distinct transcriptional subtypes, defined by the differential expression of surface antigens such as SEZ6, DLL3, B7-H3 (CD276), TROP2 (TACSTD2), and CEACAM5." (PMID 41149456, 2025).
Hernia (3 papers, 2022 to 2023). "In total, 24 proteins were significantly differentially expressed in 28 BCa and 12 hernia patients, with the area under the curve (AUC) of individual regions ranging between 0.702 and 0.896 and an AUC of 0.72 for tumor-associated calcium signal transducer 2 (TACSTD2)." (PMID 36407096, 2022).
uterine serous carcinoma (3 papers, 2012 to 2025). "TROP 2, tumor-associated calcium signal transducer 2 (Tacstd2), is mainly overexpressed in poorly differentiated endometrial adenocarcinoma and uterine serous carcinoma (65%)." (PMID 40731786, 2025).
asthma (2 papers, 2024 to 2025). "Another male-specific pQTL rs11207327 linked with CD5 levels also modulates the expression of genes (JUN, KRT79, TACSTD2), and it is associated with diseases and traits (Asthma, self-reported haemorrhoids and treatment with estriol product)." (PMID 38326779, 2024).
alcoholic steatohepatitis (1 paper, 2019). "In a previous study, we reported on the first RNA sequencing-based transcriptome profiles of BECs isolated from alcoholic steatohepatitis patients through EpCAM- or TROP2-based FACS sorting (respectively epithelial cell adhesion molecule (TACSTD1) and trophoblast antigen 2 (TACSTD2)." (PMID 31547151, 2019).
amyloid (1 paper, 2024). "Taken together, the results of transcriptome analysis and immunofluorescence staining of post-LSCT corneal sample with amyloid deposits obtained during keratoplasty demonstrated complete restoration of wild-type TACSTD2 expression, indicating that donor CECs replaced host CECs." (PMID 39013858, 2024). "To determine whether amyloid deposition recurs after LSCT due to incomplete replacement of host CECs by donor CECs, we analyzed the expression of wild-type TACSTD2 at the RNA and protein levels in the post-LSCT corneal sample with amyloid deposits obtained during keratoplasty." (PMID 39013858, 2024).
cyst (1 paper, 2024). A sac-like closed membranous structure that may be empty or contain fluid or amorphous material. "We identified a small number of genes with altered expression before visible cyst formation including Tumor associated calcium signal transducer 2 (Tacstd2)." (PMID 39666736, 2024). "Through our multispecies, multiomic approach, we identified 74 cyst initiation candidates including tumor-associated calcium signal transducer 2 (Tacstd2)." (PMID 39666736, 2024). "Similar to what we observed in our murine models, TACSTD2 was only faintly detected in control tissues but was strongly observed in the cyst-lining epithelial tissue from cystic patients and overall levels of TACSTD2 signal were higher in the cystic kidneys." (PMID 39666736, 2024). "Human tissue biopsies and organoids show that TACSTD2 protein is low in normal kidney cells but is elevated in cyst lining cells, making it an excellent candidate for mechanistic exploration of its role in cyst initiation." (PMID 39666736, 2024). "The insights gained from studies of breast and other aggressive cancers suggest that Tacstd2 is a promoter of cell proliferation and could play a key role in cyst formation." (PMID 39666736, 2024). "It is possible that Tacstd2/TACSTD2’s role in cyst initiation may depend on developmental timing." (PMID 39666736, 2024). "Nonetheless, even if Tacstd2 is an early consequence rather than a cause of cyst formation, its role as a marker of cystic epithelium could prove beneficial for targeting anti-cyst therapies to affected tissues." (PMID 39666736, 2024). "Importantly, this study does not establish whether Tacstd2 is necessary or sufficient for cyst initiation, a question that will be addressed in future research." (PMID 39666736, 2024).
cystic kidneys (1 paper, 2024). "In conclusion, our work demonstrates that Tacstd2 is elevated early in cystic kidney tissue as well as human polycystic kidneys." (PMID 39666736, 2024). "In addition, to see how Tacstd2 responds in more highly cystic kidneys, we examined P21 tissue collected from another study where Pkd2 was deleted in the early post-natal period by tamoxifen treatment of mothers nursing Rosa26-CreERT2, Pkd2flox/flox pups." (PMID 39666736, 2024).
Parkinson disease (1 paper, 2025). A progressive degenerative disorder of the central nervous system characterized by loss of dopamine producing neurons in the substantia nigra and the presence of Lewy bodies in the substantia nigra and locus coeruleus. "The GSEA results suggest that ENTPD1, SERPINA1, and TACSTD2 may be involved in the occurrence and development of PTC by jointly regulating the spliceosome, Parkinson’s disease, and cytokine–cytokine receptor interaction pathways." (PMID 40520228, 2025).
tumor (362 papers, 2008 to 2026). "TACSTD2, also known as Trop2, is a transmembrane glycoprotein associated with tumor invasion and proliferation." (PMID 40520228, 2025). "TACSTD2 and EpCAM were previously reported to be associated with cell adhesion and metastasis of tumor, implying the effect on recurrent MPE accompanied with CLDN4." (PMID 38629624, 2024). "Trophoblast cell surface antigen 2 (Trop-2), a 40-kDa glycoprotein also known as tumor-associated calcium signal transducer-2, plays a crucial role in the development and metastasis of various solid tumors." (PMID 38519953, 2024). "Notwithstanding these limitations, our data strongly points to the association of TACSTD2 expression with a worse prognosis, a more “hot” tumor immune microenvironment, and a unique mutational landscape among cancers profiled." (PMID 38986529, 2024). "Next, the association of TACSTD2 expression levels with the tumor immune landscape was investigated, revealing several significant associations (P < .05)." (PMID 38986529, 2024). "Our single-cell analysis revealed that BRAF V600E mutation tumor epithelial cells highly expressed TACSTD2 and CLDN3, which were then validated in TCGA data." (PMID 34805166, 2021). "Another example of surface molecule involved in NEPC development is represented by Trop2, a tumour-associated calcium signal transducer 2 (TACSTD2)." (PMID 34940756, 2021). "With a membranous expression of Tumor-associated calcium signal transducer 2 (Tacstd2, Trop-2) of at least 10% of tumor cells, tumors are classified as positive." (PMID 34768978, 2021). "We identified the tumour‐associated calcium signal transducer 2 (TROP2) to be the most strongly up‐regulated gene on OIV compared with MS which was confirmed by qPCR analysis." (PMID 32283567, 2020). "Loss of adhesion molecule ICAM1, gain in TACSTD2 expression, and increased tumor cell–ECM interaction under DAPK1 loss seem to be central events in this process." (PMID 31772156, 2019). "There is a large body of evidence to suggest that tumor-associated calcium signal transducer 2 (also named Trop2; encoded by TACSTD2) promotes cellular proliferation, and this gene is highly expressed in a wide variety of epithelial tumors." (PMID 30696739, 2019). "Strikingly, the abnormal localization of CLDN1 and OCLN that we documented following TACSTD2 silencing both in hepatoma cell lines and in primary human hepatocytes was analogous to that observed in tumor tissue of patients with HCV-associated HCC." (PMID 29538454, 2018). "The expression of TACSTD2 was significantly associated with tumor TNM stage (P=0.020), local recurrence (P=0.002) and distant metastasis (P=0.001)." (PMID 25202389, 2014). "DNA isolated from peripheral blood samples was subjected to polymerase chain reaction (PCR) followed by direct sequencing to detect mutations in the tumor-associated calcium signal transducer 2 (TACSTD2) gene." (PMID 20454699, 2010). "Finally, modulation of haemostasis-related factors such as MDK and TACSTD2 further inhibited angiogenesis and tumour-associated signalling." (PMID 41516237, 2025). "In addition, we discovered that TACSTD2 was significantly increased in samples from tumor patients and had better diagnostic value than CEA." (PMID 38698420, 2024). "Pan-cancer characterization of the molecular landscape associated with TACSTD2 may help expand the application of TROP2-targeting agents into additional tumor types and identify possible therapeutic cotargets." (PMID 38986529, 2024). "In our study, we found that the cancer cells in the pleural effusion exhibited the phenotype of circulating tumour cells (CTCs) and expressed metastatic markers such as Epithelial Cell Adhesion Molecule (EpCAM) and Tumour Associated Calcium Signal Transducer 2 (TACSTD2)." (PMID 38629624, 2024). "The association of TACSTD2 expression with OS was investigated in each tumor type." (PMID 38986529, 2024).
tumor (continued). "It is also probable that the tumor suppressor role of TACSTD2, documented in our study, is associated with the resulting suppression of the synthesis of intranucleolar ribosomal RNA and the nuclear translocalization of TACSTD2 in the presence of GSE1 downregulation." (PMID 34439112, 2021). "Whether TACSTD2 is tumor specifically hypermethylated in RCC or shows association of methylation with adverse clinicopathological parameters and survival of patients has not been investigated at yet." (PMID 33882870, 2021). "Moreover, hypermethylation of TACSTD2 has been associated in all these tumor entities with subsequent epigenetic silencing and, in addition, coincided with adjacent organ invasion, poor differentiation and reduced OS." (PMID 33882870, 2021). "Similarly, a subpopulation of tumor cells isolated from prostatectomy specimens express higher levels of tumor-associated calcium signal transducer 2 (Trop2), CD44, and CD49f, and show increased sphere-forming ability and regeneration capability in mice." (PMID 32754615, 2020). "TACSTD2 was significantly overexpressed in the tumour tissues of OC patients compared to those of healthy controls." (PMID 41331197, 2025). "CD24, CLDN3, WFDC2, and TACSTD2 genes were present in all the tumour clusters of all samples, and the genes C1orf194, C20orf85, MS4A8, ODF3B, RSPH1, and TPPP3 appear to be co‐expressed." (PMID 41160707, 2025). "In vivo experiments have demonstrated that TACSTD2 promotes tumour growth and progression, including increased invasiveness and malignancy." (PMID 41331197, 2025). "Although the functions of TROP2 overexpression are well studied and are associated with tumor aggressiveness, EMT, metastasis and decreased overall survival, little is known about the regulation of TACSTD2 expression." (PMID 38302503, 2024). "In this multi-omic analysis of a large pan-cancer cohort, we observed significant tumor type-specific differences in the landscape of molecular alterations as well as a more immune-enriched, or “hot,” microenvironment in TACSTD2-high tumors." (PMID 38986529, 2024). "In summary, the expression of TACSTD2 in diverse solid tumor makes the use of TROP2-directed ADCs an attainable potential target for these tumor types." (PMID 38986529, 2024). "The in silico analysis revealed an increased association of the active H3K4me3 mark with the TACSTD2 promoter when the tumor had high TROP2 expression." (PMID 38302503, 2024). "TACSTD2 levels are increased in elderly serum and tumor serum and can be used as a biomarker for aging and tumors." (PMID 38698420, 2024). "The 5 tumor types selected for analysis were based on their representation of a broad expression of TACSTD2." (PMID 38986529, 2024). "Since we observed a differential immune landscape associated with TACSTD2 expression, OS following treatment with ICI was investigated across tumor types." (PMID 38986529, 2024). "The co‐expression of any 1 gene from Group A (C19orf33, S100A14, and RHOD; count ≥1) and any 1 gene from Group B (CST6, CD44, TM4SF1, and TACSTD2; count ≥1) in a single tumor cell was defined as a MIC." (PMID 38864342, 2024). "Clinicians ought to be aware of the broad, tumor-agnostic translational relevance of TACSTD2/TROP2 as a potential therapeutic target." (PMID 38986529, 2024). "High-expressing ERBB2 tumors have an increased expression of antibody drug conjugate (ADC) target genes NECTIN4 and TACSTD2 versus the low-expressing ERBB2 tumor." (PMID 38136267, 2023). "Tumour subclones with the mutation TOP1, known to encode topoisomerase-1 and the mutation TACSTD2, the encoder for TROP2, were found." (PMID 37631232, 2023). "Lastly, tumour-associated calcium signal transducer 2 (TROP2), encoded by the (TACSTD2) gene, is a transmembrane glycoprotein expressed in approximately 80% of TNBC." (PMID 36176752, 2022).